UCP1 (uncoupling protein 1)
Diseases named in the same sentence as UCP1 in open-access papers (continued):
Sharing a sentence is not in itself a finding about the gene and the disease.
metabolic syndrome (27 papers, 2006 to 2025). A cluster of metabolic risk factors for CARDIOVASCULAR DISEASES and TYPE 2 DIABETES MELLITUS. "Similar results were also observed in obese mice, where CDCA supplementation reduced glucose intolerance and dyslipidemia by inducing UCP1-mediated thermogenesis in brown adipose tissue." (PMID 38275628, 2023). "Unlike WAT, BAT is known to play a critical role in energy homeostasis and thermogenesis in mammals, thereby protecting against diet-induced metabolic syndrome and hypothermia via the action of uncoupling protein 1 (UCP1)." (PMID 34501754, 2021). "In contrast, CME ameliorated HFD increased body weight, hyperglycemia, dyslipidemia, ketonemia, hepatic tissues lipid peroxidation, restored hepatic tissue architecture and enhanced protein expression of leptin, adiponectin and UCP1 and activity of hepatic GR." (PMID 32197395, 2020). "This study indicated that HFD increased food intake and body weight gain and induced dyslipidemia and hyperglycemia in rats through reducing leptin, adiponectin and UCP1 protein production." (PMID 32197395, 2020). "The other possible cause of HFD induced increased body weights, hyperglycemia and dyslipidemia in the current study is the reduction of leptin, adiponectin and UCP1 protein expression, which play important roles in the regulation of food intake, insulin sensitivity and energy metabolism." (PMID 32197395, 2020). "In addition, we found that co-treatment with simvastatin improved olanzapine-induced dyslipidemia, inhibited transcriptional levels of Hmgcr, Srebp1 and Fasn, and reversed the decreased levels of UCP1 and PGC-1α in BAT by olanzapine treatment." (PMID 32605639, 2020). "The aim of this study was to investigate the changes in uncoupling protein 1 (UCP1) level in psoriasis patients and evaluate its possible role in the pathogenesis of the disease, focusing on disease severity (Psoriasis Area and Severity Index), dyslipidemia, inflammation, and cardiovascular risk." (PMID 40104293, 2025). "AMPK phosphorylation, elevated uncoupling protein 1 (UCP1), and insulin-like growth factor binding protein 1 (IGFBP-1) protein levels in WAT in pu-erh tea also suggest its potential to modulate metabolic syndrome and improve WAT browning." (PMID 40647906, 2025). "We also studied the control of the expression of UCP1, -2, and -3 in abdominal WAT from metabolic syndrome rats treated with (RSV + QRC)." (PMID 33670130, 2021). "We found that in metabolic syndrome rats, the mostly-expressed isoform was UCP2, low levels of UCP3 were present, and UCP1 was undetectable." (PMID 33670130, 2021). "This study indicated that CME ameliorated HFD induced hyperglycemia and dyslipidemia through normalization of HFD reduced leptin, adiponectin and UCP1 proteins production and antioxidant activity." (PMID 32197395, 2020). "UCP-1 is crucial to brown and beige adipocyte function and beiging of WAT represents an important approach to alleviate dyslipidemia." (PMID 32317752, 2020). "Although protein expression in BAs from Il18−/− mice, which was significantly different such as UCP1, was not affected by rIL-18 administration, in Il18−/− mice, dyslipidemia was improved by short-term (2 weeks) rIL-18 administration." (PMID 30453990, 2018).
Hyperglycemia (21 papers, 2009 to 2026). An increased concentration of glucose in the blood. "This notion is supported by experiments showing that overexpression of uncoupling protein-1 (UCP-1) abolished the proton electrochemical gradient driving oxidative phosphorylation and prevented hyperglycemia-induced ROS production." (PMID 31581464, 2019). "Taken together, these observations concerning UCP1 amounts and activity are therefore contrary to any hypothesis regarding a role for leptin-induced UCP1-mediated glucose combustion in BAT or brite/beige fat in the leptin-induced amelioration of hyperglycemia." (PMID 31743040, 2020). "Moreover, overexpression of Ucp-1, which is a specific protein uncoupler of oxidative phosphorylation capable of collapsing the proton electrochemical gradient, also prevented the effects of hyperglycemia." (PMID 33922704, 2021). "Therefore, lower irisin levels in the T2DM and MetS groups could reduce the expression of UCP1, decrease oxidative metabolism, and favor hyperglycemia." (PMID 32964051, 2020). "Moreover, studies indicated that UCP-1 overexpression could eliminate the production of hyperglycemia-induced reactive oxygen species (ROS) in cultured mouse glomerular mesangial cells, and upregulation of UCP-1 was beneficial for DKD rats." (PMID 29849705, 2018). "Overexpression of uncoupling protein-1 (UCP-1) and manganese SOD (MnSOD) have been shown to reverse hyperglycemia-induced phenotypes in multiple cell types." (PMID 30408422, 2018). "Studies have shown that when mitochondrial voltage is impaired by uncoupling protein 1 (UCP-1) or when superoxide is degraded by manganese superoxide dismutase (MnSOD), hyperglycemia does not activate these pathways." (PMID 39634174, 2024). "Hyperglycemia-induced sorbitol accumulation is wholly prevented by thenoyltrifluoracetone (TTFA), uncoupling protein 1 (UCP-1) and manganese superoxide dismutase (Mn-SOD), indicating that mitochondrial superoxide overproduction stimulates aldose reductase activity." (PMID 39148537, 2024). "If the mitochondrial potential is normalised in the cells by uncoupling protein-1 (UCP-1) overexpression or the mitochondrial respiratory chain is inactivated by mitochondrial DNA depletion hyperglycemia does not generate superoxide." (PMID 27565382, 2016). "We also reported that hyperglycemia did not change UCP1 gene expression in HUVEC but upregulated it in HMVEC (though non-significant, p = 0.06)." (PMID 24093550, 2013). "Also, overexpression of uncoupling protein 1 (UCP-1) or MnSOD showed that hyperglycemia did not activate any of these pathways." (PMID 39201524, 2024).
Hypertension (20 papers, 2007 to 2024). The presence of chronic increased pressure in the systemic arterial system. "Three of them (Crp, Fabp1, and Ucp1), known as associated with hypertension, were expressed only in adrenal glands from hypertensive rats." (PMID 28105924, 2016). "Therefore, activating UCP-1 has been suggested to exert a positive effect on weight loss, preventing hypertension and improving oxidative stress and other metabolic states." (PMID 35178098, 2022). "Importantly, alpha-lipoic acid supplementation prevented the development of hypertension and reduced epididymal fat weight by a mechanism associated with the increase of epididymal UCP-1 protein expression." (PMID 31888243, 2019). "In conclusion, BAT UCP1 mRNA expression is reduced in older, obese people with hypertension and impaired glucose homoeostasis, in keeping with defective BAT thermogenesis." (PMID 38917410, 2024). "The tail blood pressure of UCP1−/− mice was higher than that of WT and TRPV1−/− mice after the 8th month, and TRPV1 knockout further accelerated and elevated the development of hypertension in a UCP1 knockout background." (PMID 35043013, 2022). "While studies of the PRAT UCP1 expression profile are scarce, the available evidence shows alteration of UCP1 expression in PRAT adipocytes in disease conditions such as hypertension and renal cell carcinoma." (PMID 34408726, 2021). "This study showed that ZDF rats exhibited hypertension and insulin resistance, accompanied by an increase in body weight and epididymal fat weight and a decrease in epididymal UCP-1 protein expression." (PMID 31888243, 2019). "Three of these genes (Crp, C-reactive protein, pentraxin-related; Fabp1, fatty acid binding protein 1, liver; Ucp1, uncoupling protein 1 (mitochondrial, proton carrier)) are known as related to hypertension development." (PMID 28105924, 2016). "Notably, the HFD-induced hypertension was further worsened in UCP1-DKO mice when compared with the controls." (PMID 36457800, 2022). "Ucp1 over-expression in aortic smooth muscle cells causes hypertension and increases dietary atherosclerosis without affecting cholesterol levels." (PMID 29064389, 2017). "This study was designed, therefore, to investigate whether a dietary supplementation of LA could prevent hypertension, insulin resistance, the increase in O2•− production in skeletal muscle, adiposity and the alteration in visceral UCP-1 protein expression in ZDF rats, a model of type 2 diabetes." (PMID 31888243, 2019). "Tests of association for additional traits (such as hypertension and coagulation factors) that were not part of our a priori hypotheses for either UCP1 or UCP2 were conducted during automated analytical procedures." (PMID 17397545, 2007). "Apolipoprotein E (ApoE) knockout mice with BMP4 knockout in adipose tissue or brown adipose tissue (aP2-DKO or UCP1-DKO, respectively) were used for exploring the role of impaired PVAT metabolism in hypertension." (PMID 36457800, 2022). "However, in UCP1 knockout mice, when the inhibitory effect of TRPV1 on LETM1 disappeared, the knockout of TRPV1 reversely aggravated mitochondrial calcium disorder and subsequent ROS production in BAT, which led to the development of hypertension." (PMID 35043013, 2022). "In this study, we found that TRPV1 knockout alone did not increase ROS production or the occurrence of hypertension in WT mice, but the knockout of TRPV1 further exacerbated ROS production in the BAT of UCP1 knockout mice." (PMID 35043013, 2022).
atherosclerosis (19 papers, 2007 to 2025). A disease characterized by the build-up of fatty material and calcium deposition in the arterial wall resulting in partial or complete occlusion of the arterial lumen. "The study in Semenkovich’s laboratory demonstrated that UCP-1 generated ROS from vascular smooth muscle cells leads to elevated ROS, reduced NO bioavailability and accelerated atherosclerosis in mice on an ApoE deficient background." (PMID 24252331, 2013). "UCP1 is activated by PPARα and PPARγ has been shown to inhibit atherosclerosis by reducing vascular inflammation." (PMID 40753563, 2025). "In a previous study, UCP1 pigs were treated under high-fat/high-cholesterol (HFHC) diet conditions for 13 months to test the protective role of UCP1 on atherosclerosis." (PMID 36688695, 2023). "Recent research has revealed that UCP1 has a protective role against vascular dysfunction and atherosclerosis by inhibiting the activation of Nod-like receptor family pyrin domain-containing 3(NLRP3) inflammatory vesicles in PVAT." (PMID 38155947, 2023). "In this work, we provided new insights into the active phenotype of BAT in CIH-induced atherosclerosis and demonstrated that UCP1- mediated lipolysis is involved in this process." (PMID 34765657, 2021). "In the present study, we identified a previously unidentified function of UCP1 in protection against vascular dysfunction and atherosclerosis, through its inhibition of MMP and mtROS-induced activation of NLRP3 inflammasome in PVAT." (PMID 34878840, 2021). "The mitochondrial protein UCP1 has potent therapeutic effects on vascular inflammation and atherosclerosis." (PMID 34878840, 2021). "UCP-1 demonstrated protective properties in atherosclerosis." (PMID 39061983, 2024). "At the same time, knock-in of Ucp-1 in pigs alleviated the severity of atherosclerosis in animals." (PMID 39061983, 2024). "Interestingly, activated BAT and increased browning of WAT in Apoe-/- mice exacerbate atherosclerosis, and genetic deletion of Ucp1 in Apoe-/- mice has been reported to prevent atherosclerotic plaque growth." (PMID 36831200, 2023). "Furthermore, we demonstrated that pharmacological interventions targeting the UCP1/MMP/NLRP3 inflammasome–IL-1β axis are promising therapeutic strategies for the treatment of atherosclerosis in small- and large-animal models." (PMID 34878840, 2021). "CIH exposure decreased the expression level of SOD and GSH, indicating that oxidative stress also participating in the process of CIH-induced atherosclerosis and it may act with UCP1." (PMID 34765657, 2021). "Importantly, ApoE−/− atherosclerosis mice had decreased expression of UCP1, PGC1α, PRDM16, Cidea, and RPS3A." (PMID 30131868, 2018). "In addition to fat synthesizing enzymes, ranolazine also normalized the expression and protein levels of the fat oxidizing enzyme, Ucp1, in failing hearts of B6 mice with chronic pressure overload and ApoE-/- mice with advanced atherosclerosis." (PMID 21711241, 2011). "Furthermore, reintroduction of UCP1 in iBAT did not revert the increased atherosclerosis in UCP1-deficient mice, implying that the vascular regulation by UCP1 can be attributed, at least in part, to UCP1 in PVAT." (PMID 38155947, 2023). "Furthermore, reconstitution of UCP1 in iBAT did not reverse the exacerbated atherosclerosis in UCP1-deficient mice, indicating that the vascular modulation by UCP1 is at least partially attributed to UCP1 in PVAT." (PMID 34878840, 2021). "First, by using a CIH-induced atherosclerosis mouse model, we demonstrated that BAT is activated with upregulated UCP1." (PMID 34765657, 2021). "It was believed that uncoupling protein 1 (UCP-1) in vascular smooth muscle cells plays an important role in ROS production and atherosclerosis." (PMID 24252331, 2013).
atherosclerosis (continued). "In addition, we also propose that the expression of uncoupling protein-1 (UCP-1) in the vascular tissue and the expression of adhesion molecules (integrins) will be low and thus, the occurrence of atherosclerosis will be decreased in transgenic fat-1 mouse." (PMID 20042103, 2009).
Glucose intolerance (19 papers, 2018 to 2025). Glucose intolerance (GI) can be defined as dysglycemia that comprises both prediabetes and diabetes. "Glucose intolerance was not different between genotypes at ambient temperature; however, in association with the increased body weight, it was higher in the UCP1 KO mice compared to the WT mice at thermoneutrality." (PMID 37240054, 2023). "The irisin-dependent effect of browning WAT is mediated by the expression of uncoupling protein 1 (UCP1), and the changes that accompany this process include stimulation of fatty acid oxidation, improvement of glucose intolerance and finally increased energy expenditure." (PMID 33271939, 2020). "The long‐term GMI treatment ameliorated fat mass accumulation, glucose intolerance, and systemic inflammation (AST) (P < 0.05) in skeletal muscle, while enhancing thermogenesis (UCP1) (P < 0.01) in eWAT." (PMID 39132696, 2024). "In summary, compared to wild-type mice, GPR17 -/- mice of the 129 strain displayed increased expression of UCP-1 in white adipose tissue, lower body weight and fat content, and resistance to HFD-induced glucose intolerance." (PMID 34646232, 2021). "Here, we found that combination of DMPP and icilin improved diet-induced glucose intolerance equally in DIO WT and DIO UCP1 KO mice." (PMID 30353008, 2018). "Likewise, compared with the vehicle group, mice fed with doxycycline to induce LETMD1 in UCP1 KO beige adipocytes had significantly increased VO2, energy expenditure and improved glucose intolerance." (PMID 39897567, 2025). "Here, we find that the ability of DMPP and the combination of DMPP and icilin to reverse diet-induced glucose intolerance is independent of BAT UCP1 induction." (PMID 30353008, 2018). "Our data demonstrated that an LPD-induced increase in FGF21 may be related to overexpression of UCP1 in BAT, resulting in improvement of glucose intolerance in WFRs." (PMID 29507597, 2018). "Surprisingly, EPA remained effective in reducing body weight and fat mass and attenuating glucose intolerance in the KO model (assessed by two-way ANOVA and without statistical consideration of sex), indicating that the effects of EPA are independent of UCP1 in both males and females." (PMID 34829779, 2021).
breast carcinoma (17 papers, 2011 to 2026). "Conversely, UCP1 expression is reduced in breast cancer and positively associated with patient survival." (PMID 40983641, 2025). "We investigated the association of tumor hypoxia, FABP7, and UCP1 across breast cancer patients using METABRIC and TCGA data sets." (PMID 32647572, 2020). "Current research linking breast cancer-associated adipocyte browning (elevated UCP1/thermogenic markers) to tumour progression and cachexia is limited by over-reliance on preclinical models, neglected subtype-specific differences, and unclear crosstalk between exosomes/ADM." (PMID 41498391, 2026). "In studying the role of UCP1-overexpressing cancer-associated fibroblasts (hTERT-BJ1) in human breast cancer cell (MDA-MB-231) growth, a previous study has demonstrated increased β-oxidation, ketone body production, and the release of ATP-rich vesicles, all of which “fuel” tumor growth." (PMID 30621584, 2019). "Furthermore, UCP1 expression has been observed to be increased in cancer-associated fibroblasts (CAFs) adjacent to breast cancer tissue, resulting in lipid mobilization and increasing ketone body production, which promotes tumor growth by supplying high-energy nutrients in a paracrine manner." (PMID 31500658, 2019). "Breast cancer cell-derived adrenomedullin (ADM) enhances the expression of UCP1 in adipocytes and promotes the phosphorylation of hormone-sensitive lipase (HSL), thereby stimulating lipolysis and the browning of adipocytes." (PMID 41498391, 2026). "Those researches showed a therapeutic potential of UCP1 on cancer through glucose and lipid metabolism regulation, whereas the mitochondrial regulation potential of UCP1 on breast cancer was insufficient." (PMID 35541900, 2022). "The electron microscope images demonstrated that the mitochondria were swelling, its' cristae structures were disappeared, which tends to a mitochondrial structure destroyed phenotype in UCP1 stable overexpressed breast cancer cell line." (PMID 35541900, 2022). "Co-culturing breast cancer cells and mature adipocytes decreases lipid droplet size, number, triglyceride content, and adipogenic marker PPARγ, while increasing UCP-1 levels and lipolytic activity." (PMID 35186923, 2022). "Transwell assay revealed that the CsA treatment impaired the positive effect of UCP1 on migration and invasion in breast cancer cells." (PMID 35541900, 2022). "Other effects and mechanisms on the regulation of UCP1 on breast cancer, especially in triple-negative breast cancer, were still urgently needed." (PMID 35541900, 2022). "For more than a decade (130 months), comparing the breast cancer patients with low UCP1 expression, high UCP1 expression individuals have a higher rate of disease-free survival and overall survival." (PMID 35541900, 2022). "Collectively, these results show that FABP7 knockdown upregulates UCP1 in the breast cancer cells presumably by inducing beige fat-like differentiation under normoxia." (PMID 32647572, 2020). "Immuno-labeling of breast cancer sections and co-culture experiments of breast cancer mammospheres with lipid-laden cells showed that UCP1 was detected in adipocytes close to the tumor cells." (PMID 32819314, 2020). "We showed that the uncoupling protein UCP1 was expressed in adipocytes close to tumor cells on breast cancer histological sections as well as in adipocytes in contact with the mammospheres." (PMID 32819314, 2020). "UCP1, which is generated only in beige/brown adipocytes, is also elevated in the adipose tissue close to breast cancer tissue." (PMID 31500658, 2019). "We found a significant increase in UCP1 expression in breast cancer cell lines, so we analyzed UCP1 expression in human breast carcinomas." (PMID 21935467, 2011). "We confirmed the large increase in UCP2 expression and also found a significant increase in gene expression of UCP1 and 5 in the rho0 cells and breast cancer cell lines." (PMID 21935467, 2011).